QPCTL (glutaminyl-peptide cyclotransferase like)
Description:
Responsible for the biosynthesis of pyroglutamyl peptides.
Synonyms: gQC; FLJ20084
Tractability: Small molecule: a structure with a bound ligand is known; a high-quality ligand is known. Antibody: UniProt predicts a signal peptide or a membrane-spanning region. PROTAC: its protein half-life has been measured; a small molecule that binds it is known.
Target class: Enzyme; Transferase
Gene: Protein-coding gene on chromosome 19 (45,692,403 to 45,703,989, forward strand). Ensembl gene ENSG00000011478.
Subcellular location: Golgi apparatus membrane
Subcellular location (Human Protein Atlas): Golgi apparatus
Gene Ontology:
Molecular function: glutaminyl-peptide cyclotransferase activity; zinc ion binding
Biological process: peptidyl-pyroglutamic acid biosynthetic process, using glutaminyl-peptide cyclotransferase
Cellular component: Golgi apparatus; membrane; Golgi membrane
Genetic constraint (gnomAD): Loss-of-function variants: 31 observed, 32.58 expected, observed/expected ratio (o/e) 0.95, 90% interval 0.71 to 1.28. The upper end of that interval is the gene's LOEUF score, 1.28, which puts it in group 5 of 6, group 1 being the genes least tolerant of losing a copy. Missense variants: 474 observed, 503.82 expected, observed/expected ratio (o/e) 0.94, 90% interval 0.87 to 1.01. Synonymous variants: 223 observed, 220.1 expected, observed/expected ratio (o/e) 1.01, 90% interval 0.91 to 1.13.
Homologues: Orthologues: chimpanzee QPCTL (99% identical), macaque QPCTL (98% identical), pig QPCTL (90% identical), rabbit QPCTL (89% identical), dog QPCTL (89% identical), guinea pig QPCTL (88% identical), rat Qpctl (85% identical), mouse Qpctl (84% identical), zebrafish qpctla (52% identical), zebrafish qpctlb (49% identical), tropical clawed frog qpctl (48% identical), Drosophila melanogaster isoQC (37% identical), and 4 more. Paralogues in human: QPCT (45% identical).
Diseases named in the same sentence as QPCTL in open-access papers:
QPCTL is named in the same sentence as 8 diseases in open-access papers, as found by Europe PMC text mining. Sharing a sentence is not in itself a finding about the gene and the disease. The quoted sentences say what the papers report.
Alzheimer disease (2 papers, 2023). A progressive, neurodegenerative disease characterized by loss of function and death of nerve cells in several areas of the brain leading to loss of cognitive function such as memory and language. "Aside from cancer, targeting QPCTL has been widely studied in Alzheimer’s disease as it modified the forms of amyloid-β (Aβ) oligomers to catalyze the generation of pyroglutamate-Aβ (AβpE3), which is more neurotoxic." (PMID 37063864, 2023). "At present, inhibitors that regulate QPCTL include SEN177 and PQ912 has entered clinical trials as a candidate for Alzheimer's disease." (PMID 37484024, 2023).
glioma (2 papers, 2017 to 2023). A benign or malignant brain and spinal cord tumor that arises from glial cells (astrocytes, oligodendrocytes, ependymal cells). "For example, we did not verify the functions of QPCTL in all the gliomas by experiments; we just cited the previous CRISPR result." (PMID 37063864, 2023).
chronic kidney disease (1 paper, 2023). Impairment of the renal function secondary to chronic kidney damage persisting for three or more months. "In chronic kidney disease, chronic treatment with QPCTL inhibitor PQ529 is a novel and effective approach for glomerulonephritis." (PMID 37063864, 2023).
tumor (6 papers, 2020 to 2026). "In cancer, QPCTL is a promising immunotherapy target since QPCTL-mediated CD47 pyroglutamylation prevents macrophages from phagocytosing tumor cells." (PMID 41988205, 2026). "This modification in tumor cells depends on the activity of glutaminyl cyclase (QPCTL) and can be inhibited pharmacologically by the pan-glutaminyl cyclase inhibitory molecule SEN177." (PMID 32240171, 2020). "In this review, we highlight the role of QPCTL in tumor evasion and immune modulation." (PMID 41988205, 2026). "An interesting report had highlighted that the role of Glutaminyl cyclase isoenzyme (QPCTL) is critical for pyroglutamate formation on CD47 at the SIRPα binding site and inhibition of QPCTL activity enhances antibody-dependent cellular phagocytosis and cellular cytotoxicity of tumor cells." (PMID 39318624, 2024). "Another emerging strategy to impede CD47/SIRPα interactions is the pharmacological inhibition of glutaminyl cyclases, especially glutaminyl-peptide cyclotransferase like protein (QPCTL), which is highly expressed in tumor cells." (PMID 36052078, 2022).
cancer (4 papers, 2020 to 2026). A tumor composed of atypical neoplastic, often pleomorphic cells that invade other tissues. "As is mentioned in a recent study, glutaminyl-peptide cyclotransferase-like protein (QPCTL) is identified as a new target to interfere with the CD47 pathway and promotes the efficacy of antibody therapy of cancer." (PMID 32161718, 2020).
metabolic disease (1 paper, 2026). A congenital disorder (due to inherited enzyme abnormality) or acquired (due to failure of a metabolically important organ) disorder resulting from an abnormal metabolic process. "These insights highlight QPCTL's potential as a therapeutic target in oncology, metabolic diseases, and immune-mediated disorders." (PMID 41988205, 2026).
QPCTL also shares sentences with these, for which no sentence is quoted: anemia (1 paper); glomerulonephritis (1).